TNF (tumor necrosis factor)
Diseases named in the same sentence as TNF in open-access papers (continued):
Sharing a sentence is not in itself a finding about the gene and the disease.
Anxiety (560 papers, 2006 to 2026). Intense feelings of nervousness, tension, or panic often arise in response to interpersonal stresses. "MCP-1 and TNF-α showed associations with anxiety severity that were restricted to the clinical group." (PMID 41835967, 2026). "It is noteworthy to mention that even certain psychopathological conditions in mothers, such as peripartum depression and peripartum anxiety, have been revealed to be associated with increased serum levels of Interleukin-6, TNF- α, and IL-8." (PMID 40242671, 2025). "This study investigated the associations between responses to competitive anxiety and salivary biomarkers-cortisol (sCort), interleukin-6 (sIL-6), and tumor necrosis factor-alpha (sTNF-α)-in elite female karate athletes during competition." (PMID 42238605, 2025). "Our results showed that TNF-a was positively associated with anxiety, consistent with previous research findings." (PMID 39757257, 2025). "Our results suggest the existence of immune–personality signatures in healthy older dogs, specifically involving serum TNF-α and IL-10 levels in association with fear- and anxiety-related traits." (PMID 40867746, 2025). "Increased levels of cytokines, such as IL-6 and TNF-α, have been linked to anxiety-related brain regions including the prefrontal and limbic systems." (PMID 40964431, 2025). "Variations in TNF-α are also associated with state anxiety in oncologic patients and their family caregivers." (PMID 40766923, 2025). "Anxiety and depression are linked to increased levels of pro-inflammatory cytokines such as TNF-α and IL-6." (PMID 41462928, 2025). "The levels of TNF-α were positively associated with the anxiety score (Spearman’s rho = .201, p = .045), obsessive–compulsive symptoms (Spearman’s rho = .222, p = .035)." (PMID 39757257, 2025). "Specifically, TNFα mediated the association between BMI z‐score and working memory only in adolescents, whereas in adults, cortisol and anxiety mediated this association." (PMID 40650919, 2025). "In utero, exposure to elevated concentrations of TNF-α is associated with an increase in anxiety and depressive-like symptoms in male mice offspring, whereas it was found to protect against anxiety in female offspring." (PMID 38586283, 2024). "The present study found that elevated TNF-α levels was a risk factor for anxiety mood in MSA patients even after adjusting age and age at onset (r = 0.340, p < 0.001)." (PMID 39295596, 2024). "The increase in ·OH and TNF-α and the decrease in NO are all associated with more severe anxiety in PD patients." (PMID 38755545, 2024). "Anxiety and depressive-like behaviors have been found to be linked to elevated levels of cytokines, such as TNF-α, in both the HC and striatum." (PMID 38911248, 2024). "The steroid therapy caused particular anxiety, since studies have shown that steroids are more likely to cause infections than anti-tumor necrosis factor (TNF)-α or other immunomodulators." (PMID 36698148, 2023). "Two of the themes formulated through the evidence synthesis were broadened (work disability: a loss of self-esteem and anti-TNF: hope re-ignited despite concerns), and a new theme – COVID-19: uncertainty and anxiety during the pandemic, was developed." (PMID 37608395, 2023). "Among these patients, two SNPs (rs1799964 and rs3093662) were identified in the tumour necrosis factor-alpha (TNF-α) gene showing association with their anxiety levels." (PMID 35528795, 2022). "Meanwhile, it has been reported that the imbalance between PGRN and TNFα contributes to thigmotaxis/anxiety caused by sleep deprivation." (PMID 35318322, 2022). "Breese’s research confirmed that IL-1β and TNF-α are involved in the sensitized anxiety response caused by repeated alcohol withdrawal." (PMID 36539796, 2022). "Increased anxiety has been reported in LPS models, which can be exacerbated by stress, and is associated with central TNF expression, as was detected here." (PMID 34991643, 2022).
Anxiety (continued). "A previous study reported that anxiety-like behavior in obese mice was associated with increased levels of TNF-α, IL-1β, and IL-6 in the brain." (PMID 35209199, 2022). "Multiple studies have linked TNFα with anxiety-like behavior in other animal models and human studies, but less is known about serum IL-17A and anxiety-like behavior." (PMID 35216112, 2022). "Following RSDS, anxiety-like behaviors are associated with increased levels of peripheral cytokines, including IL-2, IL-10, IL-17A, IL-22, and TNFα." (PMID 35927237, 2022). "In particular, inflammatory processes seem to be involved in these symptoms; indeed, pro-inflammatory cytokines, such as TNF-α, are associated with anorexia, weight loss, locomotors retardation, anxiety, and decreased social exploration." (PMID 34067632, 2021). "Elevated IL-6 and TNF-α have been shown to increase the activity of the amygdala—the region associated with anxiety and depressive symptoms." (PMID 34575258, 2021). "Consistent with previous literature reports, our results found that IL-6 and TNF-α were significantly important in their association with pregnancy anxiety and function as drivers of inflammation." (PMID 34360332, 2021). "The results showed that CCI caused mechanical hyperalgesia and depressive and anxiety-like behaviors in rats and neuroinflammation in the amygdala, such as an increased protein level of TNFα and IL-1β and activation of astrocytes." (PMID 34025342, 2021). "The baseline TNF-α level was correlated with the improvement in depressive symptoms, particularly the symptoms of anxiety/somatization and weight loss." (PMID 33364982, 2020). "At baseline, a significant correlation was found between the HAM-D-24 subdomains of anxiety/somatization and weight loss and the TNF-α levels." (PMID 33364982, 2020). "In a national database with 2861 participants, higher C reactive protein (CRP) levels were similarly associated with somatic and cognitive symptoms of anxiety in male subjects, while IL-6 and TNF-a levels were associated with somatic symptoms of anxiety." (PMID 32824625, 2020). "Risk factors for migraine were a high level of anxiety, female sex, young age, and TNF-alpha inhibitor treatment (OR = 1.90 (1.13–3.25))." (PMID 32560321, 2020). "Accordingly, a long-term HFD (16 weeks) has been shown to cause anxiety, increase corticosterone level, and increase inflammatory cytokines, such as interleukin-6, interleukin-1β, and tumor necrosis factor-α." (PMID 32209056, 2020). "Human volunteer studies with bacterial endotoxin show an association between plasma TNF-α and acute changes in anxiety." (PMID 27633985, 2017). "In mice, sustained inflammatory pain, with concomitant TNF-α increase in basolateral amygdala, was associated with anxiety-like behaviours which was reversed by local infusion of infliximab, a TNF-α neutralizing antibody." (PMID 26881136, 2016). "On the contrary, the MH and EWB scores were found to be independently and negatively associated with history of anxiety and the levels of cortisol and TNF-α (all P < 0.05)." (PMID 27861337, 2016). "In the general population, anxiety symptoms were associated with increase of several inflammation markers, including C-reactive protein, TNF-α, and IL-6, even after adjusting for multiple confounding factors." (PMID 26881136, 2016). "For instance, a previous study demonstrated that P. berghei-infected mice exhibit anxiety-like symptoms associated with increased brain levels of IL-1β and TNF, and histopathological changes in brainstem, cerebrum and hippocampus." (PMID 24180288, 2013). "Additionally, the levels of TNF-α showed a significant positive association with the anxiety score (Spearman’s rho = 0.201, p = 0.045) and OCS (Spearman’s rho = 0.222, p = 0.035)." (PMID 39757257, 2025). "Specifically, higher TNF-α was associated with higher anxiety symptoms in females only." (PMID 40485934, 2025).
Anxiety (continued). "Elevated IL-6 and TNF-α levels are frequently associated with depressive and anxiety symptoms." (PMID 41302239, 2025). "Moreover, a recent preclinical study has demonstrated that sustained TNF signaling is associated with the development of anxiety-like behaviors." (PMID 40485934, 2025). "Serum TNF-α and IL-6 levels in MSA patients may be associated with anxiety symptom; however, only TNF-α was shown to be a useful tool in distinguishing between MSA and HCs." (PMID 39295596, 2024). "Furthermore, anxiety triggers inflammatory processes by causing high levels of pro-inflammatory cytokines such as IL-6, IL-1β, and TNF-α." (PMID 39720795, 2024). "Interestingly, high levels of IL-6 and TNF-α in the brain have been associated with anxiety behavior in rodents." (PMID 39720795, 2024). "Furthermore, using TNF-α deficient mice, we demonstrated that the diminished neurogenesis and anxiety-like behaviour observed after HBV vaccination require TNF-α derived from CD8+ T cells." (PMID 39386089, 2024). "Besides, pro-inflammatory cytokines such as TNF-α, and IL-6 were significantly associated with anxiety scores." (PMID 38902708, 2024). "Furthermore, inflammatory processes are triggered by anxiety, which is caused by high levels of pro-inflammatory cytokines such as IL-6, IL-1β and TNF-α." (PMID 38255283, 2024). "In addition, the elevated TNF-α and IL-6 levels were associated with anxiety symptoms in MSA patients, and further studies with longitudinal and prospective designs from multiple centers and ethnic populations are required to verify these preliminary findings." (PMID 39295596, 2024). "Anxiety was positively associated with TNF-α on D1 (P=0.024) and D3 (P=0.013)." (PMID 37878890, 2023). "It has been proposed that these sex differences in anxiety‐like behavior and reduced learning may be caused by enhanced expression of pro‐inflammatory molecules (TNFα, IL6) and neuroinflammation in the brain of aged female mice." (PMID 37675802, 2023). "In addition, magnolol attenuated naloxone-precipitated heroin withdrawal, prevented rapid wight loss and anxiety-like behavior associated with naloxone-precipitated heroin withdrawal, and attenuate heroin-induced increase in striatal TNF-α concentration." (PMID 37112606, 2023). "That blocking TNF signaling just within the ventral hippocampus is sufficient to prevent the stress-induced anxiety would argue that these synaptic changes in the ventral hippocampus are causative for the stress-induced increase in anxiety-like behavior." (PMID 36104437, 2022). "While this could be a direct relationship to anxiety, IFNγ was also related to serum TNFα and IL-17A, the latter of which was also significantly associated with both hippocampal IL-17A and to anxiety-like behavior." (PMID 35216112, 2022). "In addition, TNF-α, IL-1β, and IL-17 were positively associated with HADS-A score, while only high TNF-α was associated with anxiety occurrence." (PMID 35239774, 2022). "Results demonstrated that women receiving the M-O-M-STM intervention had longitudinally sustained lower TNF-α/IL-10 ratios than the control group, and it was significantly associated with psychosocial measures of anxiety, specifically for fears of labor and spouse/partner relationships." (PMID 34360332, 2021). "These pro-inflammatory cytokines (such as IFNγ or TNFα) then reach the brain via the humoral, neural and cellular routes, where they cause the already mentioned shift in balance from M2 to M1 activation in microglia (or macrophages), thus, causing anxiety." (PMID 33970950, 2021). "In particular, as anxiety is associated with an increased production of pro-inflammatory cytokines, including tumor necrosis factor-alpha (TNF-α) and interleukin-6 (IL-6), the effect of n-3 PUFAs of decreasing inflammatory cytokines indirectly promote the reduction of anxious symptoms." (PMID 32839416, 2020).
Anxiety (continued). "The network showed that interleukin 6 (IL-6) and tumor necrosis factor (TNF) were most associated with the DE mRNAs and miRNAs, which suggested that inflammatory factors might play an important role in chronic pain with anxiety." (PMID 32655622, 2020). "Interestingly, we found that two subdomains (anxiety/somatization and weight loss) of the depressive symptoms showed significant correlations with TNF-α levels." (PMID 33364982, 2020). "Likewise, administering TNF intracerebrovascularly causes overt anxiety in normal mice, whereas etanercept given by the same route is anxiolytic in a mouse model of multiple sclerosis." (PMID 29725287, 2018). "Thus, the excess release of TNF-α in the hippocampus activated the JAK2-STAT3 signalling pathway that is closely associated with anxiety-like behaviours." (PMID 28336920, 2017). "This may be important since elevated CNS pro-inflammatory cytokines, including IL-1β and/or TNFα, have been associated with increased anxiety, decreased cognition, and altered social behaviors." (PMID 25212412, 2014). "In this study, evaluated whether TNFα, fibrinogen, cortisol, and anxiety mediate the association between BMI z‐score and EF performance—specifically working memory, inhibition, cognitive flexibility, and a latent EF component—in adolescents and adults, using a moderated multiple mediation approach." (PMID 40650919, 2025). "Notably, HSP resulted in a significant attenuation of anxiety- and depression-associated behaviors, a reduction in pro-inflammatory cytokine levels (TNF-α, IFN-γ, IL-1β, IL-2, IL-6), and an augmentation of neurotrophic factors (NT-3, BDNF, NGF) within the striatum." (PMID 41346684, 2025). "Furthermore, ·OH and TNF-α were the risk factors of anxiety for PD patients." (PMID 38755545, 2024). "However, whether the increase in hippocampal TNF is instructive to stress-related synaptic modulation and associated anxiety-like behaviors remains unexplored." (PMID 36104437, 2022). "In addition, a normal cognitive function under initial conditions relies on TNF and its receptors deficiency of TNF improves spatial learning and memory and reduces anxiety levels in mice, whereas knockdown of TNF receptor-increase exploration and anxiety-like behavior." (PMID 36389810, 2022). "Similarly, anxiety-like behavior during experimental MS has been linked to both an IL-1β-dependent alteration of endocannabinoid and GABAergic striatal signaling and a tumor necrosis factor α (TNF-α)-induced alteration of striatal glutamatergic transmission." (PMID 33922780, 2021). "Zhang further found that PCW attenuated anxiety-like behaviors in chronic sleep-deprived (CSD) rats by suppressing TNF-α/NF-κB signaling." (PMID 41535967, 2026). "In mice, SFDF improved memory and learning, alleviated anxiety-like behavior, reduced IL-6, TNF-α, and lipid peroxidation, and enhanced antioxidant defenses." (PMID 41705257, 2026). "In CIS rats, XYS treatment, comparable to the JAK2 inhibitor AG490, alleviated anxiety-like behavior, reduced hippocampal damage, and inhibited activation of the TNF-α/JAK2-STAT3 pathway." (PMID 41535967, 2026). "Previous rodent studies affirm that elevated TNF-α impairs maternal motivation and pup-directed behaviors, while serotoninergic dysregulation exacerbates postpartum anxiety and caregiving deficits." (PMID 41399726, 2025). "Stress-induced anxiety was reported to increase TNF-a levels and to reduce the expression of the S1P receptor 2 in hippocampal tissue of rats which affects immune cell trafficking, among others." (PMID 40042667, 2025). "Ethanol exposure increased anxiety and immobility in behavioral tests, consistent with depressive-like behaviors, and elevated TNF-α, IL-1β, and IL-6 levels." (PMID 40860877, 2025). "The research aimed to study the effects of 4‐AP on anxiety‐like behavior induced by SD, while examining the potential role of hippocampal TNF‐α, NMDA‐R, AMPA‐R, and oxidative stress markers (MDA and TAC) in this process." (PMID 40059459, 2025).
Anxiety (continued). "This investigation reveals that inflammatory markers like TNF-α and IL-6—triggered by chemotherapy—as well as hormonal fluctuations intensify psychological distress, including anxiety, depressive symptoms, and social isolation." (PMID 40688105, 2025). "Using the elevated plus maze, treated mice exhibited reduced anxiety-like behavior and lower IL-6 and TNF-α systemic levels in blood samples." (PMID 40342368, 2025). "Preclinical studies support these actions, showing reductions in anhedonia and anxiety-like behaviors after TNF-α blockade." (PMID 40943274, 2025). "The meta-analysis confirmed increased expression of four anxiety-related molecular mediators in response to COVID-19 infection: CALCA, TNF, PLAT, and PPARG, with the latter three associated with neurocognitive decline." (PMID 40766923, 2025). "Administration of TNF-α increases anxiety, anhedonia, and depressive feelings in humans and rodents." (PMID 40766923, 2025). "HH induced enhanced anxiety-like behaviors and reduced spontaneous activity, accompanied by elevated levels of L-1β, IL-6, and TNF-α in both serum and hypothalamus." (PMID 41222826, 2025). "Moderated multiple mediation analyses with mediators in parallel were conducted (X: BMI z‐score; M: cortisol, anxiety, TNFα, and fibrinogen; Y: executive functions; Moderator: adolescent and adult groups)." (PMID 40650919, 2025). "In the present study, we found small but significant (p = 0.001) predictive effects of serum TNF-α and IL-10 levels on fear- and anxiety-related personality traits, moderated by age." (PMID 40867746, 2025). "In mice exposed to acute stress, hippocampal microglia tend to release higher levels of tumor necrosis factor alpha (TNF-α) and IL-1B, which inhibits neurogenesis and promotes neural apoptosis, thus enhancing anxiety behaviors." (PMID 40507852, 2025). "Studies have shown that Gardenia jasminoides J. Ellis can improve sleep quality and alleviate anxiety symptoms by modulating the gut microbiota and reducing levels of TNF-α and IL-7β." (PMID 40395724, 2025). "Both T2DM and cancer are characterised by elevated secretion of proinflammatory cytokines (e.g., IL-6, TNF-α, IL-1β), which can cross the blood–brain barrier and activate microglia, thereby contributing to depressive and anxiety symptoms." (PMID 41149069, 2025). "Preclinical models corroborate these mechanisms, showing reductions in anhedonia and anxiety-like behaviors after TNF-α blockade." (PMID 40943274, 2025). "At a molecular level, TNF can reduce the availability of monoamines which has been suggested to link with the mechanism of anxiety." (PMID 39757257, 2025). "Animal studies also found that COX2 inhibition is associated with a reduced increase in the proinflammatory cytokines TNFα and IL1β together with lower anxiety and cognitive decline." (PMID 40352929, 2025). "Cytokine Inhibitors: Targeted therapies such as IL-6 inhibitors (e.g., tocilizumab) and TNF-α blockers have shown promise in reducing anxiety symptoms in patients with high inflammatory markers." (PMID 40218134, 2025). "In another mouse model, TPs improved recognition ability and reduced anxiety-like behaviors by suppressing TNF-α production." (PMID 40551742, 2025). "Only Hamilton Anxiety Scale (HAMA) has a positive correlation between with TNF-α in MSA patients with age and age at onset as covariates." (PMID 39295596, 2024). "Taken together, these results suggest that the deleterious effects of HBV on hippocampal neurogenesis and anxiety-like behaviour are mediated by increased TNF-α production." (PMID 39386089, 2024). "Binary logistic regression analyses showed that the levels of ·OH, NO, and TNF-α in serum were correlated with anxiety in patients with PD." (PMID 38755545, 2024). "We also observed a Spearman correlation between systemic MCP-1/TNF alpha in curcumin-treated patients and moderate anxiety [Anx-Cur (After), p < 0.05]." (PMID 39334711, 2024).